AR (androgen receptor)
Diseases named in the same sentence as AR in open-access papers (continued):
Sharing a sentence is not in itself a finding about the gene and the disease.
breast carcinoma (continued). "In the future, further studies in vivo and in vitro should be conducted to identify the functional mechanism of miR-3163 in AR positive breast cancer." (PMID 34797837, 2021). "In prostate and breast cancers, AR activation can be achieved also by a ligand-independent signaling through receptor tyrosine kinases such as epidermal growth factor receptor (EGFR)." (PMID 34681618, 2021). "Accumulating evidence has attracted attention to the androgen receptor (AR) as a biomarker and therapeutic target in breast cancer." (PMID 34736512, 2021). "We therefore evaluated the efficacy and safety of combining the anti-HER2 therapy trastuzumab with enzalutamide in patients with HER2+ AR+ locally advanced breast cancer or MBC." (PMID 33591468, 2021). "Recent preclinical studies have demonstrated that selective AR modulators (SARMs) have promising anti-proliferative activity in ER+ breast cancer models." (PMID 33671468, 2021). "GT0918 was demonstrated to effectively suppress the expression of AR protein and the growth of AR-positive breast cancer tumors in mouse xenograft tumor models." (PMID 34392453, 2021). "Previous reports showed that AR is expressed in approximately 60.5% of breast cancer (4658/7693) and is involved in multiple signaling pathways to modulate cellular processes; thus, it is a promising drug target in clinical applications." (PMID 34073224, 2021). "Compared to previous studies, we firstly investigated the further radiomics analysis using multi-parametric MRI including DCE, T2-weighted images (T2WI), and ADC images for the breast cancer molecular subtype classification and AR expression." (PMID 34490107, 2021). "The androgen receptor (AR) is expressed in ~70–90% of invasive human breast cancers, a frequency comparable to or higher than those reported for ER (70–80%) and PR (50–70%)." (PMID 33681329, 2021). "Most studies focusing on anti-AR therapy in breast cancer are based on AR expression in neoplastic cells, evaluated with immunohistochemistry." (PMID 33534004, 2021). "Breast cancer (BC) is the most common malignancy in female, but the role of androgen receptor (AR) in triple-negative breast cancer (TNBC) is still unclear." (PMID 34797837, 2021). "Like androgen receptor, the role(s) of the glucocorticoid receptor in breast cancer is not fully understood." (PMID 34680352, 2021). "The AR polymorphism characterized by longer AR-CAG repeats within the AR gene and resulting in a deficient AR activity, has been associated with an increase in breast cancer risk at an early age in patients carrying the BRCA-1 mutation." (PMID 35008851, 2021). "AR expression varies between breast cancer subtypes, and the function of AR in breast cancer is highly context-dependant, contingent on the co-expression of ER, the AR:ER protein ratio, the menopausal status of the patient and the hormonal milieu." (PMID 34638457, 2021). "Accumulated data have demonstrated the important role of AR-signaling in breast cancer tumorigenesis and disease progression." (PMID 34392453, 2021). "When compared to other TCGA intrinsic subtype cohorts (HER2, luminal A, and luminal B) and a SMMART-program cohort (40 metastatic breast cancers), AR was moderate, while ESR1 was low." (PMID 33772089, 2021). "DHEA can act as an inducer of the proliferation of estrogen and androgen receptor-positive breast cancer cells, and inhibit the proliferation of estrogen receptor-negative cells." (PMID 34678978, 2021). "Inhibition of CBP and p300 as a means to block the transactivation activity of the AR and ER is an emerging therapeutic strategy for prostate and breast cancers." (PMID 34201346, 2021). "Taken together, our data suggest that p68 and PDGFR-β co-regulate AR expression and mediate androgen dependent proliferation in breast cancer cells." (PMID 34659545, 2021). "It was discovered that AR agonists can inhibit proliferation of AR-positive breast cancer, except in ER-negative and HER2-positive breast cancer." (PMID 33915941, 2021).
breast carcinoma (continued). "Contrary to the action of androgens which mediate their effects through androgen receptor (AR), expression of AR has been shown to be a favorable prognostic indicator in breast cancer." (PMID 34234742, 2021). "Our preclinical data demonstrated that GT0918 inhibited the growth of AR-positive breast cancer xenograft tumors." (PMID 34392453, 2021). "To understand the mechanism by which PDGFR-β regulates AR expression in breast cancer cells, we examined the levels of PDGFR-β in MDA-MB-231 cells upon PDGF-BB stimulation." (PMID 34659545, 2021). "The identification and understanding of interactions among adipokines and the androgen receptor in cancer cells are necessary to guide the development of new therapeutic approaches in order to prevent and cure obesity and breast cancer." (PMID 34066328, 2021). "Combined with the present findings, the future clinical use of serum PSA as a biomarker for tumor AR activity in breast cancer is promising." (PMID 34736512, 2021). "X chromosome aneusomy and related AR gene copy number aberrations have been demonstrated in male breast cancer." (PMID 33534004, 2021). "GT0918, the 2nd-generation AR antagonist, has potential antitumor effect in AR-positive breast cancer." (PMID 34392453, 2021). "Like ER, androgen receptor (AR) is expressed in the majority (~85%) of breast cancers and is positively correlated with FOXA1 expression, yet its role in breast cancer is less understood." (PMID 34680352, 2021). "This open-label, single-arm, phase II study evaluated the efficacy and safety of enzalutamide, an AR-signaling inhibitor, in patients with advanced HER2+ AR+ breast cancer previously treated with trastuzumab." (PMID 33591468, 2021). "Using AR-positive breast cancer cell lines representing all breast cancer subtypes, expression of candidate factors was assessed in response to agonist DHT and antagonist enzalutamide." (PMID 34736512, 2021). "AR expression is associated with poor response to neoadjuvant chemotherapy in ER-positive breast cancer, and patients with AR-positive or LAR breast cancer also have poor pathological clinical response to neoadjuvant chemotherapy when compared to other TNBC." (PMID 34736512, 2021). "AR on the other hand is present in about 80 % of breast cancers making it more commonly expressed than either ER or PR, and plays an important oncogenic role in breast cancer." (PMID 34421361, 2021). "Although some similarities exist between the role of AR in DNA damage repair in prostate and breast cancers, a full characterization of the similarities and differences is still ongoing." (PMID 33062889, 2020). "Ample data have indicated that AR promotes PTEN gene expression in breast cancer and that targeting AR alone suppresses PTEN activity, thus activating the PI3K pathway." (PMID 32587770, 2020). "In the current study, we showed the favorable prognostic effect of AR expression on both overall survival and disease-free survival in breast cancer." (PMID 32290220, 2020). "Advancements in this mechanistic understanding will shed light on potential combination therapies and will allow for more effective treatment for patients with AR+ breast cancers." (PMID 33062889, 2020). "Since AR expression has important consequences on the prognosis and treatment of breast cancer, further studies with an increased number of samples is necessary to confirm our reports." (PMID 32374753, 2020). "The ratio between AR and ER IHC staining has been suggested to be informative as to the functional role of the AR pathway in breast cancer." (PMID 33613616, 2020). "Breast cancer is a hormone-driven malignancy that expresses various sex steroid receptors such as ER beta, PR, and androgen receptor, in addition to the classical hormonal marker ER alpha." (PMID 32380759, 2020). "The Androgen Receptor (AR) is emerging as an important factor in the pathogenesis of breast cancer (BC), which is the most common malignancy among females worldwide." (PMID 31952272, 2020).
breast carcinoma (continued). "Preclinical studies have shown that an AR antagonist, enzalutamide, reduces breast cancer proliferation in HER2+, trastuzumab-resistant cell lines." (PMID 35582612, 2020). "In ERa+ breast cancer, we identified different colocalization patterns (nuclear or cytoplasmatic) with PR and AR on the luminal epithelium." (PMID 33266334, 2020). "Our three LAR PDX models were resistant to the AR inhibitor enzalutamide and to standard chemotherapy for breast cancer (combination of anthracyclines and cyclophosphamide)." (PMID 32042320, 2020). "Luminal androgen receptor (LAR) breast cancers account for about 10% of all TNBCs; anti-AR therapy was proposed for this subset of TNBCs, but the clinical benefit was limited." (PMID 32210163, 2020). "In ERα-positive/HER 2-positive breast cancers, where AR is expressed in more than 60% of cases, studies have suggested that AR positivity is responsible for smaller tumor sizes, lower Ki67 percentages, and less aggressive phenotypes." (PMID 31952272, 2020). "In breast cancer, expression and activation of AR is increasingly recognized for its role in cancer development and its importance in promoting cell growth in the presence or absence of estrogen." (PMID 33062889, 2020). "Three of these genes belonged to the PAM50 set: AR, FOXA1, and GPR160, while the remaining genes had all been individually associated with breast cancer subtypes." (PMID 32605588, 2020). "Another phase II clinical study evaluating enzalutamide in combination with transtuzumab in patients with HER2+ AR+ metastatic or locally-advanced breast cancer (NCT02091960) is ongoing." (PMID 31952272, 2020). "Triple-negative breast cancer cell lines with the highest AR expression were selected for subsequent study, including MDA-MB-453, ACC-422, and SUM-18528." (PMID 32117061, 2020). "UCD12 (formerly PT12 cells) are ER+ have been used to study mucin secretion dynamics, anti-AR therapies, and endocrine resistance in diet-induced obesity models of breast cancer." (PMID 32576280, 2020). "Recent preclinical studies suggest a bifunctional role of AR in breast cancer, with a growth promoter activity in tamoxifen-resistant cancer, and a growth inhibitor function in tamoxifen-sensitive breast cancer." (PMID 32210163, 2020). "Some previous works have colocalized ERa and PR in breast cancer or ERa and AR with other markers in colon cancer using optical microscopy and multispectral detection using non-IVD primary and different species-specific secondary antibodies." (PMID 33266334, 2020). "In contrast, AR is involved in tamoxifen resistance in ER+ breast cancers and AR inhibitors are under clinical trial." (PMID 33266334, 2020). "Evaluation of the role of androgen receptor (AR) in the biology of breast cancer is an emerging area of research." (PMID 32374753, 2020). "Not only ERs but also other receptors such us progesterone receptor (PR), human Her2, and AR play important prognostic and predictive roles in the pathogenesis of breast cancer." (PMID 33317149, 2020). "Another example is the androgen receptor (AR), a key transcription factor in the development of breast cancer." (PMID 32268558, 2020). "This is the first study on AR expression in breast carcinoma in Sri Lanka and despite the limitations, these findings add to the evidence that AR positivity is a widespread aspect of breast cancer that deserves therapeutic attention and further study." (PMID 32928183, 2020). "It has been reported that AR can be stabilized by USP14, and depletion of USP14 reduces cell proliferation by blocking the G0/G1–S phase transition in AR-responsive breast cancer cells." (PMID 32268558, 2020). "While AR expression has been increasingly recognized in AR+, ER− breast cancers, the specific role of AR signaling is not well understood." (PMID 33062889, 2020). "The androgen receptor is expressed in more than 70% of primary breast cancers; usually, its expression is correlated to ERα and PgR." (PMID 31952272, 2020).
breast carcinoma (continued). "A study that conducted a systemic review reported that AR-positive tumors accounted for 60.5% of all breast cancers, with a wide range of 28% to 84%." (PMID 32290220, 2020). "The high AR expression group was significantly associated with superior overall survival and disease-free survival when compared with the low AR expression group in breast cancer patients." (PMID 32290220, 2020). "Many studies indicated co-expression of AR with the hormonal receptors in breast cancer has a favorable prognosis." (PMID 32374753, 2020). "The androgen receptor (AR) and its related pathways are emerging as a therapeutic target in breast cancer, and the possibility of AR-targeted therapy in breast cancer is under active investigation." (PMID 32290220, 2020). "AR expression and its signaling pathway have been reported to have an important role in the pathogenesis and progression of breast cancer." (PMID 32290220, 2020). "The prevalence of AR positivity was 40.8% among this cohort of Sri Lankan women with early breast cancer." (PMID 32928183, 2020). "The cytoplasmic ligand-dependent transcription factor androgen receptor (AR) has gained increasing attention as an important marker of breast cancer (BC) biology." (PMID 32344660, 2020). "Accordingly, breast cancer subtype has also been reported to be a crucial factor in terms of AR prognostication." (PMID 32290220, 2020). "These inconsistencies in the literature regarding the prognostic role of AR in breast cancer precipitated this study." (PMID 32290220, 2020). "AR expression is reported to be closely related to clinicopathologic parameters of breast cancer and also related to the prognosis of patients to breast cancer." (PMID 32290220, 2020). "The study of PDXs that were isolated from ER+ breast cancers consistently contributed to clarify the role of AR in these tumors." (PMID 32210163, 2020). "In this study, we investigated the prognostic role of AR in breast cancer patients and looked at both overall survival and disease-free survival." (PMID 32290220, 2020). "In other studies, however, breast cancer patients with AR+ tumors have better overall survival at both 3 and 5 years compared to patients with AR− tumors, regardless of ER expression." (PMID 33062889, 2020). "In ER+ breast cancer, AR binds at an ARE located in the promoter of the ERβ gene, resulting in increased ERβ expression." (PMID 33062889, 2020). "Various authors have reported a relationship between AR positivity in a triple-negative subtype of breast cancer and a high or low frequency of lymph node metastasis, high or low proliferative activity, tumor size, and low survival rate." (PMID 32373367, 2020). "This work demonstrates additional clinical applications for AR targeting agents in the treatment of breast cancer." (PMID 32117061, 2020). "In conclusion, we report here that the stem cell pluripotency factor Sox2 is commonly expressed in feline mammary carcinomas, is associated with higher proliferation, decreased PR and FOXA1, but higher AR expression, as well as poor outcomes." (PMID 33553286, 2020). "LIN28A promoted cell proliferation and invasion and suppressed cell apoptosis in ER−/Her2+ breast cancer cells and accelerated breast cancer xenograft tumor growth in vivo by activating androgen receptor (AR) via recruiting c-myc to AR promoter region." (PMID 33381451, 2020). "Additional studies are needed to better understand use of antiandrogen therapies for the treatment of women with AR+ breast cancers." (PMID 33062889, 2020). "Co-expressing AR and ER in breast cancer improved disease-free survival (DFS) and overall survival (OS) significantly." (PMID 32374753, 2020).
breast carcinoma (continued). "In breast cancer patients, the highest average AR pathway activity score was found in the HER2 subtype." (PMID 33613616, 2020). "Androgen receptor (AR) is an emerging therapeutic target in breast cancer where it is expressed in majority (60–80%) of breast cancers with higher prevalence in ER-α+ tumors." (PMID 32484822, 2020). "This study investigated the prognostic role of AR in breast cancer using tissue microarrays from 395 patients with operable primary breast cancer." (PMID 32290220, 2020). "Further, in breast cancer, both AR and ER require similar cofactors for the activation of common signaling pathways." (PMID 33062889, 2020). "Several studies found, however, expression of the AR in 60–85% of breast cancers, and in some patients even at higher levels than the ER." (PMID 32218303, 2020). "In the first phase 2 study of metastatic AR-positive TNBC breast cancer patients, bicalutamide, an AR antagonist, showed a six-month clinical benefit rate of 19% [95% CI, 7–39%] and a median PFS of 12 weeks (95% CI, 11–22 weeks)." (PMID 32846967, 2020). "Previously, it has been shown that [18F]FES and [18F]FDHT uptake correlate well with ER and AR expression levels in representative breast cancer biopsies." (PMID 32307594, 2020). "Herein, through a review of preclinical studies, clinical studies, and clinical trials, we summarize the biology of AR, its prognostic and predictive value, as well as its therapeutic implications by breast cancer molecular subtype." (PMID 31952272, 2020). "In breast cancer, hormonal receptors for estrogen (ER), progesterone (PR) and androgens (AR) can be used as a target for non-invasive whole-body evaluation of the hormonal status and to predict the response of cancer to endocrine treatment." (PMID 32218303, 2020). "Taken together, these results show that AR provides new opportunities for the treatment of this subset of breast cancer patients." (PMID 31952272, 2020). "Meanwhile, SIRT1 activation in BRCA1 overexpressed breast cancer cells inhibited AR expression and AR-stimulated cancer cell proliferation." (PMID 33330467, 2020). "The recent discovery of the luminal androgen receptor subtype of triple-negative breast cancer has highlighted the importance of these sex steroid receptors in breast cancer classification and therapeutic decision making." (PMID 32380759, 2020). "Expression of AR is significantly associated with apocrine differentiation of salivary duct carcinomas and breast cancers indicating that AR is a surrogate marker for these histological types, and possess a promising therapeutic target." (PMID 32867793, 2020). "Preclinical and clinical studies conducted in recent years are supporting the role of AR-targeting treatment in the management of breast cancer." (PMID 32374753, 2020). "AR competes with ER at the level of ER elements that impairs ER-dependent gene transcription, and AR has been proposed as a therapeutic target in ER-α─ breast cancers that retain AR expression." (PMID 32484822, 2020). "Of note, the biologic effect of AR on breast cancer has been reported to be different according to the estrogen receptor (ER) status." (PMID 32290220, 2020). "This is in line with reported AR/ER expression ratios per subtype, and suggestive of a potential benefit of anti-androgen therapy for breast cancer with a high AR/ER pathway activity ratio." (PMID 33613616, 2020). "AR expression is frequently observed in breast cancer and the rate of AR positivity is reported to be 60%–80%." (PMID 32290220, 2020). "Other AR inhibitors (such as bicalutamide or enobosarm: Gtx-024) have also been combined with lapatinib to restore lapatinib-sensitivity in HER2+/HR+ breast cancer patients." (PMID 35582612, 2020). "Androgen receptor (AR) is expressed in a significant number of most types of breast cancers and is more frequently expressed than ER and PR." (PMID 32374753, 2020).